TTF1 (transcription termination factor 1)
Diseases named in the same sentence as TTF1 in open-access papers (continued):
Sharing a sentence is not in itself a finding about the gene and the disease.
squamous cell carcinoma (80 papers, 2011 to 2026). A carcinoma arising from squamous epithelial cells. "If needed (e.g. if the carcinoma is poorly differentiated), the pathologist may request additional diagnostic stains, such as TTF-1 for adenocarcinoma, p63/p40 for squamous carcinoma or mucin stain; predictive test(s) can also be requested (e.g. NGS to identify oncogenic alterations)." (PMID 35857102, 2022). "TTF1 and p63 are conventional markers for differentiating squamous cell carcinoma and adenocarcinoma." (PMID 39584166, 2024). "TTF1 had a higher sensitivity and specificity than Napsin A. Both p63 and p40 were equally sensitive for squamous cell carcinoma." (PMID 39584166, 2024). "TTF-1 and napsin A were crucial for identifying adenocarcinoma, while p63 was key for squamous cell carcinoma." (PMID 39070322, 2024). "Studies using IHC on formalin-fixed paraffin-embedded NSCLC tissues reported that TTF-1 is expressed in 75–90% of adenocarcinomas, 40% of large cell carcinomas, and 0–38% of squamous cell carcinomas." (PMID 36672660, 2023). "As expected, the majority of cells in the adenocarcinoma PDS expressed CK7 and TTF1, whereas most cells in squamous cell carcinoma PDS expressed CK5/6 and p63." (PMID 38067281, 2023). "Thyroid transcription factor 1 (TTF-1) is expressed in more than 70% of adenocarcinoma, but rarely in squamous cell carcinoma." (PMID 35625840, 2022). "Cases with squamous cell carcinoma were diagnosed with TTF-1 negativity and positive expression of p63 and p40." (PMID 35308701, 2022). "Thyroid transcription factor 1 (TTF-1) was used as a specific marker for adenocarcinomas, while tumor protein p63 (p63) is a specific marker for squamous cell carcinomas." (PMID 32485798, 2020). "Recently, patient outcome and specific oncogene mutations in LC tumors have been associated with tumor subgroups defined by positive expression of adenocarcinoma (TTF-1/Napsin A) or squamous cell carcinoma (CK5/P40) immunohistochemistry markers." (PMID 26124082, 2015). "Although p63 positivity is often used as a marker of squamous cell carcinoma in diagnostic pathology, we found that a few ALK-rearranged tumors coexpressed p63 and TTF1 in the adenocarcinoma component." (PMID 23922677, 2013). "Most cytopathology laboratories currently employ an IHC panel in these cases as an adjunct to aid tumor sub-classification, including TTF-1, Napsin A (positive in adenocarcinoma), cytokeratin 5/6 and P63 (positive in squamous cell carcinoma)." (PMID 22547449, 2012). "Among them, mucin and thyroid transcription factor 1 (TTF1) are adenocarcinoma-specific proteins, whereas p63 and cytokeratins 5/6 (CK 5/6) are squamous cell carcinoma specific." (PMID 21785682, 2011). "All specimens were analysed for expression of MAdL, TTF-1, SP-A, SP-B and, in case of squamous cell carcinoma, cytokeratin 5/6." (PMID 21811254, 2011). "It has been suggested that NSCLC subtypes can be distinguished using several immunohistochemical markers, such as napsin A and thyroid transcription factor 1 (TTF-1) in adenocarcinoma and tumor protein 63 (p63) and protein 40 (p40), which are frequently expressed in squamous cell carcinoma." (PMID 39070322, 2024). "The transcription factors TTF1/NKX2-1 and ΔNp63/p40 are the counterposed molecular markers associated with the main Non-Small Cell Lung Cancer subtypes: TTF1 for adenocarcinoma, p40 for squamous cell carcinoma." (PMID 38291083, 2024). "The combination of TTF1 and p40 as a limited panel was optimal in poorly differentiated carcinomas, where 97.56% adenocarcinomas and 96.6% squamous cell carcinomas could be confidently diagnosed." (PMID 39584166, 2024). "TTF-1 is mainly expressed in glandular epithelium of the thyroid and epithelial cells of the lung, which can be used to identify pulmonary adenocarcinoma and squamous carcinoma." (PMID 37266641, 2023).
squamous cell carcinoma (continued). "In fact, IHC analysis should be limited to poorly differentiated NSCLC samples, in which thyroid transcription factor 1 (TTF‐1) and p40 expression could be helpful to determine adenocarcinoma or squamous cell carcinoma histotype, respectively." (PMID 35868633, 2022). "Diagnostic inaccuracy was often related to a squamous marker not included in the IHC panel (also seen for the scanned cases), the case being a neuroendocrine tumor, thyroid transcription factor-1 (TTF-1) expression in squamous cell carcinomas (with clone SPT24), or poor differentiation." (PMID 34827719, 2021). "Stratification of LC cases based on immunomarkers for adenocarcinoma (TTF-1/Napsin A) and squamous cell carcinoma (CK5/P40) revealed that 71% of the cases could be classified as variants of adenocarcinoma or SqCC." (PMID 26124082, 2015). "The diagnosis of squamous cell carcinoma or adenocarcinoma is based on histomorphological grounds in cases where the appearances are characteristic; additionally, immunohistochemical staining is performed using antibodies against TTF-1, p63, M-CEA and CK." (PMID 25120654, 2014). "Negativity of TTF-1 and thyroglobulin of tumour cells might be helpful in metastatic squamous cell carcinoma in the differentiation from the primary squamous cell carcinoma of the thyroid that reported exceptionally." (PMID 22933935, 2011). "Furthermore, a quantitative approach that is based on a weighted algorithm of the expression of five proteins is better at classifying NSCLC NOS into squamous cell carcinoma or adenocarcinoma than TTF1/TP63 staining." (PMID 21785682, 2011). "Interestingly, three of the four patients were redefined as adenocarcinoma or adenosquamous cell carcinoma and one patient was redefined as squamous cell carcinoma according to the 2015 WHO criteria because of positive TTF-1 and CK5/6 IHC staining, respectively." (PMID 29246019, 2017). "Compared to the mouse squamous cell carcinoma cell line KLN-205, EP cells exhibited markedly higher expression of Ttf1 and Napsa, while the expression of Krt5 and Np60 was significantly lower." (PMID 41356800, 2026). "The PDTOs were positive for subtype-specific markers; i.e., TTF-1 and CK-7 for adenocarcinomas, p63 and CK5/6 for squamous cell carcinomas, and CD56 and synaptophysin for small-cell lung cancer." (PMID 40723176, 2025). "The primary immunomarkers used to differentiate NSCLC subtypes include TTF-1 and Napsin A for adenocarcinoma, and CK5/6, p40, and p63 for squamous cell carcinoma." (PMID 40746930, 2025). "In thyroid malignancies, excluding well-differentiated thyroid cancers, the paired box gene 8 (PAX-8) protein is considered a more sensitive indicator of thyroid origin than TTF-1 or thyroglobulin; however, PAX-8 is present in limited quantities in primary squamous cell carcinomas." (PMID 40061900, 2025). "For instance, markers positive in adenocarcinoma, such as TTF-1 and Napsin A were negative, and markers positive in‌ squamous cell carcinoma, such as p40, p63 and CK5/6 were also negative." (PMID 40969808, 2025). "Positive staining for p40 and negative staining for thyroid transcription factor 1 (TTF-1) confirmed it as squamous cell carcinoma." (PMID 40698218, 2025). "The exclusion criteria were as follows: (a) the histology of the patients’ tumors was squamous cell carcinoma (n=123) and (b) the evaluation of TTF-1 expression was not conducted (n=57)." (PMID 39076994, 2024). "Tumors demonstrating strong nuclear positivity for p63 and negative staining for TTF-1 and napsin A were categorized as squamous cell carcinoma." (PMID 39070322, 2024). "They showed positive staining of neuroendocrine markers such as Chr A and CGRP or the thyroid transcription factor TTF-1 and were negative for CC-10 (Clara or club cell secretory protein) and p63 (squamous cell carcinoma)." (PMID 37894963, 2023).
squamous cell carcinoma (continued). "IHC predominantly showed weak or negative staining for markers such as TTF‐1, CK5/6, p40, synaptophysin, chromogranin A, and CD56, which are often associated with adenocarcinoma, squamous cell carcinoma, and neuroendocrine tumors." (PMID 38124509, 2023). "All tumours showed positive expression of squamous cell carcinoma markers, such as positive P63, and negative expression of adenocarcinoma markers, such as TTF1." (PMID 35832518, 2022). "It thus seems logical to distinguish TTF-1 positive non-squamous carcinomas, which would be more differentiated, from TTF-1 negative ones, which would be less differentiated." (PMID 35885495, 2022). "The tumor cells of the squamous cell carcinoma were positive for p63 but negative for TTF-1 and CK7." (PMID 34492061, 2021). "TTF-1, CK7, CK5/6, p63 and p40 are useful for typifying the majority of non-small-cell lung cancers, with TTF and CK7 being typically expressed in adenocarcinomas and the latter three being expressed in squamous cell carcinoma." (PMID 31935792, 2020). "CK5/6, P40 and P63 were all positive (100%) in the detected LELC and squamous carcinoma samples; in parallel, TTF-1, CgA and Syn were negative without exception." (PMID 31752892, 2019). "All squamous cell carcinomas (SCCs) were negative for TTF-1, but most of them were positive for HMWK (34βE12) and P63." (PMID 29531543, 2017). "At present, there are no immunohistochemical or molecular markers in routine use that reliably differentiate primary pulmonary from metastatic squamous cell carcinomas, as TTF-1 typically is not expressed in pulmonary squamous cell carcinomas." (PMID 22263108, 2012). "In their study, all poorly differentiated squamous cell carcinomas showed expression of p63 while negative for thyroid transcription factor-1 (TTF-1), whereas adenocarcinomas had the opposite staining pattern." (PMID 21776344, 2011). "Indeed, squamous cell carcinomas are usually negative for TTF-1, while the opposite is shown in adenocarcinomas." (PMID 26858029, 2016). "Negative staining for both p63 and TTF-1 usually rules out squamous cell carcinoma." (PMID 21776344, 2011). "No expression of TTF-1, MAdL, SP-A and SP-B could be observed in squamous cell carcinomas, whereas all of them displayed a positive signal for cytokeratin 5/6." (PMID 21811254, 2011). "Conversely, TTF-1-negative NSCLC cells exhibit lower differentiation and coexist with squamous cell carcinomas derived from atypical mucous column epithelial cells." (PMID 39076994, 2024). "In contrast, the distinction between TTF-1 positive and TTF-1 negative non-squamous carcinomas is more relevant." (PMID 35885495, 2022). "In contrast, the distinction between TTF-1 positive and TTF-1 negative non-squamous carcinomas seems to be clinically relevant with a more favorable prognosis in the case of TTF-1 positivity." (PMID 35885495, 2022). "Pulmonary adenocarcinoma is differentiated from squamous cell carcinoma by being typically positive for CK7 and TTF-1, and negative for p63 and CK5/6." (PMID 22263108, 2012). "In non-small-cell carcinomas, whose direction of differentiation cannot be identified on morphological examination, tumors that test positive for TTF-1 should be reclassified as NSCLC, inclined towards adenocarcinomas, regardless of the co-expression of squamous cell carcinoma." (PMID 39928773, 2025).
thyroid cancer (78 papers, 2008 to 2025). "Well differentiated thyroid cancers almost universally express the markers thyroid transcription factor-1 (TTF-1), PAX8, thyroglobulin and B-catenin; however, loss of expression of these proteins is often characteristic of ATC." (PMID 35193694, 2022). "The thyroid transcription factor TTF-1 is silenced in aggressive thyroid cancer that is associated with a loss NIS expression and iodine uptake." (PMID 31835496, 2019). "Germline mutations in TTF1 have also been shown to play a role in thyroid carcinoma, specifically in PTC." (PMID 28117295, 2017). "Loss of TTF-1 causes differentiated or poorly differentiated thyroid cancer to lose the ability to absorb, concentrate radioactive iodine, and produce thyroglobulin during progression.In previous studies, it expressed nearly 100% of PTC and follicular thyroid carcinomas." (PMID 39882267, 2024). "The present findings also reflect that tissue TG and TTF1 could be accurate diagnostic factors in thyroid carcinoma." (PMID 35203561, 2022). "These molecular findings were also supported by a series of histopathological and immunohistochemical findings that concluded that tissue TG and TTF1 could be accurate diagnostic factors in patients with thyroid carcinoma." (PMID 35203561, 2022). "The mutant TTF-1 cannot bind to the target DNA, thereby losing its regulatory function, affecting the normal differentiation and maturation of thyroid cells, and even causing malignant transformation, leading to the occurrence of thyroid cancer." (PMID 34631891, 2021). "A variant located on 14q13.3 nearest to thyroid transcription factor-1 (TTF1) predisposes individuals to thyroid cancer, but whether this variant is related to the RET/PTC rearrangement associated with human papillary thyroid carcinomas (PTCs) is unknown." (PMID 24014739, 2013). "TTF-1 and Napsin A are valuable immunohistochemical markers for diagnosing pulmonary adenocarcinoma and thyroid carcinoma, helping differentiate them from metastases of other origins." (PMID 40564811, 2025). "TTF-1, a nuclear protein encoded by the NKX2-1 gene, is highly specific for lung and thyroid carcinomas, while Napsin A, an aspartic protease, is specific for pulmonary adenocarcinomas." (PMID 40740944, 2025). "TTF-1 staining was seen in 82 of 152 tumor categories including thyroidal cancers (19–100%), adenocarcinomas (94%), neuroendocrine tumors (67%) of the lung, small cell neuroendocrine carcinomas (71–80%), mesenchymal tumors (up to 42%), and thymomas (39%)." (PMID 39377914, 2024). "Both pulmonary carcinomas and the one thyroid carcinoma consistently expressed pancytokeratin and TTF1 with intense diffuse cytoplasmic and nuclear immunoexpression, respectively." (PMID 38071286, 2023). "Of interest, the effect of PAX8 expression of cancer cell proliferation and migration is relatively minor, and TTF1 has a more pronounced effect on the tumorigenic properties of thyroid cancer cells." (PMID 35806410, 2022). "The expression of TTF-1 has also been shown to be decreased in undifferentiated forms of thyroid cancer." (PMID 36497320, 2022). "TTF1 and PAX8 are both markers of embryonic thyroid development that are often co-expressed in thyroid cancer cells, and TTF1 was shown to regulate the expression of PAX8 in thyroid cancer cells." (PMID 35806410, 2022). "TTF-1 is overexpressed in lung and thyroid carcinomas and shows higher specificity in these two organs." (PMID 35915686, 2022). "Nevertheless, TTF-1 can often assist in differentiating primary thyroid carcinoma from secondary thyroid metastases (sensitivity 93%, specificity 96%)." (PMID 35328664, 2022). "MTOR inhibition promotes the expression of thyroid-specific genes and proteins and RAI uptake with TTF1-dependent redifferentiation in thyroid cancers." (PMID 33995657, 2021). "In neuropathological routine, TTF1 immunohistochemistry is most often used to distinguish metastases of lung and thyroid cancers from primary brain tumors." (PMID 33876327, 2021).
thyroid cancer (continued). "ATC lacks most markers seen in thyroid cancer such as thyroglobulin, TTF1, NIS, and TSHR, except PAX8 that can be present consistently in squamous variant ATC but in only 50% of ATC with spindle cell features." (PMID 31835496, 2019). "In our patient, another possibility, thyroid cancer, was excluded by the finding of negativity for both thyroglobulin and TTF1, the former being highly specific to follicular neoplasms with the exception of poorly differentiated and anaplastic types." (PMID 29960592, 2018). "Deacetylase inhibitors reduced cell viability, restored NIS and H19, and suppressed the oncogenes HMGA2 and TTF1 in thyroid cancer cells." (PMID 29561759, 2018). "In thyroid cancer, TTF-1 was detectable in 100% of PTC, FTC, and FA; in 90% of poorly differentiated anaplastic carcinomas and medullary carcinomas; and in none to fewer than 25% of undifferentiated carcinomas." (PMID 29100400, 2017). "The expression of PDPN is slightly different to the expression of thyroid transcription factor-1 (TTF-1), a marker for thyroid carcinoma." (PMID 29100400, 2017). "In thyroid carcinoma as a whole it seems likely that TTF1’s molecular functions, DNA binding, and transcription activation are probably disrupted." (PMID 28117295, 2017). "TTF-1 is a nuclear transcription factor which is expressed in thyroid and lung epithelial cells and is commonly used as a marker of thyroid carcinoma, pulmonary adenocarcinoma, and pulmonary neuroendocrine neoplasms." (PMID 24062959, 2013). "In summary, we found that the thyroid cancer cells had decreased the expression of TTF-1 and HNF3β/FoxA2; and their forced re-expression was associated with decreased cell growth." (PMID 18682709, 2008). "Our present study demonstrated that forced expression of either HNF3β/FoxA2 or TTF-1 was unable to induce differentiation of the thyroid cancer cells as measured by NIS mRNA expression and radioiodine uptake." (PMID 18682709, 2008). "Real-time PCR showed that HNF3β/FoxA2, TTF-1, and Pax-8 were expressed in normal thyroid tissue; in contrast, levels were either very low or undetectable in thyroid carcinoma cell lines." (PMID 18682709, 2008). "The expression of Pax-8 and TTF-1 is low in thyroid carcinoma; and stable transfection with a Pax-8 expression vector in anaplastic thyroid carcinoma cell line, ARO, caused re-expression of endogenous NIS, TG, and TPO." (PMID 18682709, 2008). "Earlier studies using either the TG or TPO promoter found that they were activated by TTF-1 and HNF3β/FoxA2 in thyroid carcinoma cell lines." (PMID 18682709, 2008). "However, up to 36% of canine pulmonary carcinomas lack TTF-1 immunoreactivity, and in addition, thyroid carcinoma, which frequently metastasizes to the lungs, can be immunohistochemically positive in up to 80% of cases." (PMID 39902337, 2024). "Furthermore, morular areas of cribriform morular thyroid carcinoma often lack TTF-1 expression but have CDX2, CD5, and CK5." (PMID 38835742, 2024). "On the contrary, TTF1 is positive in more than 90% of thyroid cancers." (PMID 37261050, 2023). "As noted, primary differentiated thyroid cancer commonly is TG, TTF-1 and PAX8 positive." (PMID 33776925, 2021). "The low levels of TTF-1 and loss of its nuclear localization in thyroid cancer have been associated with dedifferentiation and increased malignancy, whereas the role of PAX8 in thyroid cancer is still controversial." (PMID 31750236, 2019). "Although TTF-1 (thyroid transcription factor 1) is generally considered a biomarker for lung and thyroid carcinoma, it may be positive in MNAC." (PMID 31266530, 2019). "Thyroid transcription factor 1 (TTF1 NKX2-1) missense mutation has been implicated in thyroid tumorigenesis of familial non-medullary cancer, it is responsible for an increased proliferation rate of tumor cells in a rat tumor model of thyroid cancer." (PMID 29561759, 2018). "Positive immunostaining of TTF-1 strongly indicates lung or thyroid cancer." (PMID 29904902, 2018).